PTH (parathyroid hormone)
Diseases named in the same sentence as PTH in open-access papers (continued):
Sharing a sentence is not in itself a finding about the gene and the disease.
Hypercalcemia (continued). "Elevated PTHrP levels, often associated with malignancies, can mimic the effects of PTH, leading to bone resorption and subsequent hypercalcemia." (PMID 39544891, 2024). "Parathyroid hormone (PTH) induced-suppression by increased 1,25-dihydroxyvitamin D3 levels and hypercalcemia lead to hypercalciuria, which, if untreated, can cause renal stones, nephrocalcinosis, and renal failure." (PMID 38396434, 2024). "The biochemical profile of patients with 24-hydroxylase deficiency-hypercalcaemia and especially high 1,25(OH)2D3 decreases not only PTH secretion but also parathyroid cell proliferation." (PMID 38665259, 2024). "For this reason, in the differentiation, we considered both PTH-dependent and PTH-independent causes of hypercalcaemia." (PMID 38665259, 2024). "The majority of parathyroid tumors encountered in clinical practice are identified during the diagnostic workup for pHPT, which is characterized by hypercalcemia and elevated parathyroid hormone levels." (PMID 38201419, 2024). "On the other hand, if the PTH level is decreased, malignancy is most likely the cause of hypercalcaemia, however other PTH-independent disorders should also be investigated." (PMID 39005653, 2024). "24-Hydroxylase, encoded by the CYP24A1 gene, is a crucial enzyme involved in the catabolism of vitamin D. Loss-of-function mutations in CYP24A1 result in PTH-independent hypercalcaemia with high levels of 1,25(OH)2D3." (PMID 38665259, 2024). "In a healthy body, the production of 1,25[OH]2D by the enzyme 1α-hydroxylase is regulated by the parathyroid hormone, but in hypercalcemia associated with cancer, this regulation is significantly impaired." (PMID 38920679, 2024). "PTH-mediated hypercalcemia often presents a diagnostic challenge and can require comprehensive testing to distinguish it from other causes of elevated calcium." (PMID 39669861, 2024). "A part of the patients diagnosed with CCA can have altered laboratory findings suggestive for hypercalcemia of malignancy (hypercalcemia associated with hypophosphatemia, low parathyroid hormone and vitamin D levels)." (PMID 38472961, 2024). "Primary hyperparathyroidism (PHPT) is one of the most encountered endocrine disorders, presenting with hypercalcemia and inappropriately normal to elevated parathyroid hormone (PTH) levels which is caused by hyperfunctioning parathyroid glands." (PMID 39028425, 2024). "Only the recurrence of PTH-independent hypercalcaemia after vitamin D supplementation revealed the other cause of hypercalcaemia, which turned out to be a genetic disorder of vitamin D catabolism." (PMID 38665259, 2024). "A growing prevalence of PHPT results in the identification of unusual cases of overlapping PTH-dependent and PTH-independent causes of hypercalcaemia." (PMID 38665259, 2024). "Hypercalcemia can be broadly categorized into two major categories: parathyroid hormone-mediated and non-parathyroid hormone-mediated causes." (PMID 39427404, 2024). "Hypercalcemia, hyperphosphatemia, and a high concentration of PTH associated with CKD are the key factors that induce phenotypic changes to form tunica media calcification." (PMID 39230198, 2024). "Primary hyperparathyroidism (PHPT) is characterized by excessive parathyroid hormone (PTH) secretion, causing serum hypercalcemia, osteoporosis, and ureteral calculi." (PMID 38662187, 2024). "Sarcoidosis causes a parathyroid hormone (PTH)-independent hypercalcemia due to increased 1-alpha hydroxylase activity in macrophages that form part of the granuloma." (PMID 39051296, 2024). "The proliferative parathyroid gland autonomously releases excessive parathyroid hormone (PTH), which causes hypercalcemia and related complications, such as osteoporosis, bone fracture, urinary calculi, renal failure, and neuropsychiatric symptoms." (PMID 38340242, 2024). "The diagnosis of PHPT was retained with high or uncontrolled PTH associated with hypercalcemia in 8 cases and normocalcemic PHPT was found in 2 patients." (PMID 38419822, 2024).
Hypercalcemia (continued). "Given the clinical suspicion of hyperthyroidism as the likely cause of hypercalcaemia, they recommended initiating treatment with carbimazole 15 mg once a day with serial thyroid function test, calcium and PTH monitoring." (PMID 39434928, 2024). "The finding of an elevated PTH level leads to the suspicion of hypercalcemia caused by primary hyperparathyroidism, which is more common in oncology patients than in the general population." (PMID 38920679, 2024). "The rule of threes should raise clinical suspicion, with a parathyroid mass >3 cm, severe hypercalcaemia >3 mmol/L, and PTH levels >3x the upper normal limit associated with the condition." (PMID 39087171, 2024). "Complete loss-of-function mutations in CYP24A1 cause 1,25D-mediated hypercalcemia with appropriately suppressed PTH." (PMID 39688907, 2024). "Workup for the cause revealed that he had parathyroid hormone–independent hypercalcemia with elevated levels of 1,25-dihydroxyvitamin D, suggesting a granulomatous disease." (PMID 39439809, 2024). "Low PTH and high 1,25(OH)2D3 levels are specific to the whole group of endogenous causes of vitamin D related to hypercalcaemia (including HCINF, granulomatous disease and some lymphomas); therefore, 24,25(OH)2D3 assessment is crucial for differentiation." (PMID 38665259, 2024). "Further investigation excluded the most common causes of PTH-independent hypercalcaemia, such as granulomatous disease, malignancy, and vitamin D intoxication." (PMID 38665259, 2024). "HPT was defined as an intact parathyroid hormone (PTH) level exceeding 80 pg/mL or hypercalcemia unexplained by causes other than HPT." (PMID 37351681, 2023). "Ectopic secretion of parathyroid hormone (PTH) is a rare cause of hypercalcemia in malignancy patients." (PMID 36798668, 2023). "Primary hyperparathyroidism is an endocrine disorder characterized by hypercalcemia (elevated blood calcium levels) and inappropriate PTH levels, caused by benign or cancerous tumors in parathyroid glands." (PMID 38117357, 2023). "Concerning the biochemical presentation, our patients showed marked hypercalcemia associated with PTH levels higher than 10 times the upper normal range." (PMID 37223026, 2023). "In clinical practice CYP24A1 loss-of-function mutations should be considered in patients presenting with PTH-independent hypercalcemia, hypercalciuria, and 1,25(OH)2D levels in the upper normal or elevated range." (PMID 37701149, 2023). "PHPT is the most common cause of hypercalcemia and is characterized by the excessive secretion of parathyroid hormone (PTH) from one or more parathyroid glands." (PMID 37510130, 2023). "Despite being a rare cause of hypercalcemia, measuring 1,25(OH)2D should be considered in the workup of a patient with high serum calcium levels, suppressed PTH, and normal PTHrP." (PMID 36751194, 2023). "Humans with homozygous loss-of-function SIK3 mutations show mild PTH-independent hypercalcemia, and common SIK3 variants are associated with blood calcium levels, findings that confirm the relevance of our findings in human mineral metabolism." (PMID 36862513, 2023). "Mutations in CYP24A1 can result in elevated 1,25(OH)2D causing parathyroid hormone (PTH)-independent hypercalcemia, hypercalciuria, nephrolithiasis, and nephrocalcinosis." (PMID 37701149, 2023). "Primary hyperparathyroidism (PHPT) can cause hypercalcemia secondary to high parathyroid hormone secretion." (PMID 37637517, 2023). "A 56-year-old woman with life-threatening hypercalcemia was caused by poorly-differentiated endometrial carcinoma secreting PTH with concomitant nodular goiter mimic parathyroid tumors." (PMID 36798668, 2023). "Primary hyperparathyroidism is a common endocrine disorder causing hypercalcemia and elevated parathyroid hormone (PTH) levels in ambulatory patients." (PMID 38222216, 2023).
Hypercalcemia (continued). "The index of clinical suspicion is far from being generous, but awareness is essential in order to avoid a hypercalcemia-associated life-threatening event or progressive skeletal and renal anomalies due to long-term uncorrected PTH and high calcium values." (PMID 37893182, 2023). "Vitamin D intoxication is associated with hypercalcemia, hyperphosphatemia, and suppressed PTH levels, which typically occurs with the excessive consumption (1250 μg/day to 25,000 μg/day) of vitamin D over several months to years." (PMID 37764770, 2023). "Often, multiple surgical interventions are performed over time in order not only to remove the tumour but also to control the PTH-driven hypercalcemia that represents the primary cause of morbidity and mortality." (PMID 37834940, 2023). "PHPT is characterized by hypercalcemia and elevated serum levels of parathyroid hormone (PTH) caused by an excessive production of PTH from one or more of the parathyroid glands." (PMID 37834965, 2023). "Characteristically, individuals with pHPT exhibit the biochemical hallmark of hypercalcemia, a consequence of excessive parathyroid hormone (PTH) secretion from one or more hyperactive parathyroid glands." (PMID 37370696, 2023). "A systematic review concluded that patients with APA were characterized by moderate hypercalcemia (mean 13.4 ± 2.4mg/dL) associated with elevated PTH level [median 430 (73–3242) ng/L], 6.6 times above the upper value of normal range." (PMID 36777354, 2023). "First, the most common (80%), is the secretion of PTHrP from tumors, which can cause hypercalcemia by acting similarly to parathyroid hormone (PTH)." (PMID 37033238, 2023). "Primary hyperparathyroidism (PHPT) is the most common cause of hypercalcemia and is characterized by elevated or inappropriately normal parathyroid hormone (PTH) levels." (PMID 38115826, 2023). "A new presentation of PTH-independent hypercalcemia found to be secondary to a CYP24A1 loss-of-function mutation in his sibling, Case 2, signaled the underlying cause." (PMID 37701149, 2023). "A less common cause of vitamin D-mediated parathyroid hormone-independent hypercalcemia is the loss of function mutation of the CYP24A1 gene." (PMID 37664318, 2023). "Routine postoperative investigations were significant for hypercalcaemia with corrected calcium of 3.19 mmol/L (reference range: 2.21–2.52 mmol/L) and an associated elevated parathyroid hormone (PTH) of 84 ng/L (reference range: 15–65 ng/L)." (PMID 36536367, 2022). "Routine investigations were significant for a PTH dependent hypercalcaemia; corrected calcium of 2.6 mmol/L (reference range: 2.21–2.52 mmol/L) and an associated PTH of 53.7ng/L (reference range: 15–65 ng/L)." (PMID 36536367, 2022). "Although the effects of PTH on the heart were previously thought to be due to hypercalcemia, it is now known that PTH itself causes hypertrophy in cardiac myocytes and vascular smooth muscles independent of calcium levels." (PMID 36161626, 2022). "The increased PTH levels cause hypercalcemia by increased skeletal calcium release, enhanced kidney tubular calcium reabsorption, and increased intestinal calcium absorption through PTH stimulated 1α-hydroxylation of vitamin D." (PMID 34991581, 2022). "Calcitriol and active vitamin D analogues are effective for lowering parathyroid hormone levels but are associated with even higher risks of hypercalcaemia." (PMID 34626363, 2022). "We present a case of a 53-year-old woman with a previous history of an underlying thyroid disorder, now presented with features of hypercalcemia and mildly elevated parathyroid hormone levels." (PMID 35083351, 2022). "Hallmark of hyperparathyroidism is hypersecretion of parathyroid hormone (PTH) which results in hypercalcemia and hypophosphatemia." (PMID 36544116, 2022). "It is usually associated with a consistent secretion of PTH, causing severe hypercalcemia and potentially all clinical conditions due to primary hyperparathyroidism." (PMID 35872978, 2022).
Hypercalcemia (continued). "The symptoms result from high levels of PTH and higher reabsorption of Ca from bones, renal tubules, and the gut, causing hypercalcemia." (PMID 35414046, 2022). "The next AHH case was a 75-year-old man, also with a chief complaint of appetite loss and who had PTH-dependent hypercalcemia with hypocalciuria (cCa, 13.6 mg/dL; iP, 2.2 mg/dL; Cre, 0.84 mg/dL; intact PTH, 101 pg/mL; and FECa, 0.04%)." (PMID 36099030, 2022). "Our findings demonstrated that the increased femoral bone loss was accompanied by high serum FGF23, PTH, hyperphosphatemia, and hypercalcemia in nephrectomized BKO mice drinking PBS." (PMID 35622784, 2022). "Infants with NHPT are typically symptomatic as hypercalcemia leads to poor feeding with resulting dehydration, and lethargy, while PTH excess causes skeletal demineralization." (PMID 35566721, 2022). "It is characterized by hypercalcemia associated with an elevated or inappropriately normal parathyroid hormone (PTH) serum level." (PMID 35983092, 2022). "Such an agent should have a low risk for hypercalcaemia, ectopic calcification and oversuppression of parathyroid hormone." (PMID 34626363, 2022). "Primary hyperparathyroidism (PHPT) that is characterized by elevated or inappropriately high parathyroid hormone (PTH) concentrations seems to be the main cause of hypercalcemia during pregnancy." (PMID 35745247, 2022). "Hypercalcemia is a clinical condition characterized by elevated circulating serum calcium levels either due to raised parathyroid hormone in hyperparathyroidism or due to secondary causes of hypercalcemia without elevated parathyroid hormone levels." (PMID 35083351, 2022). "In order to verify hypercalcemia caused by hyperparathyroidism, parathyroid ultrasound and parathormone (PTH) were also performed." (PMID 35379205, 2022). "Primary hyperparathyroidism (PHPT) is an endocrine disorder characterized by hypercalcemia caused by excessive parathyroid hormone (PTH) secretion from the parathyroid gland." (PMID 36161626, 2022). "In primary hyperparathyroidism (PHPT), elevated [PTH] causes hypercalcemia by increasing TRCa/Ccr; in SHPT, comparable or higher [PTH] is associated with and presumably required to achieve normal TRCa/Ccr and normocalcemia." (PMID 35913960, 2022). "The rare occurrence of non-PTH-dependent hypercalcemia associated with acromegaly is attributable to complex factors involving increased intestinal calcium absorption, enhanced bone calcium release, and reduced urinary calcium elimination." (PMID 33933067, 2021). "The diagnosis of PHPT is based upon elevated levels of both blood serum calcium and PTH, after excluding other causes of hyperparathyroidism or hypercalcemia." (PMID 34020602, 2021). "Primary hyperparathyroidism, a condition of chronically elevated parathyroid hormone (PTH) levels in the presence of hypercalcemia, has been linked to adverse effects on glucose metabolism." (PMID 33801212, 2021). "PHPT is an endocrine disorder, characterized by hypercalcemia combined with inappropriately normal or elevated parathyroid hormone (PTH) levels, which are associated with serious skeletal and renal complications." (PMID 34746197, 2021). "Many patients affected by PHPT, either in syndromic or sporadic forms, lack classical signs and symptoms traditionally associated with excessive PTH secretion and/or hypercalcemia (asymptomatic PHPT)." (PMID 34440663, 2021). "We concluded that the diagnosis was hypercalcemia caused by PTH secretion from the bone metastasis in the fibular head, and focused further treatment against the fibular tumor." (PMID 33413267, 2021). "Primary hyperparathyroidism (pHPT), the most common cause of hypercalcemia, is characterized by hypercalcemia and PTH levels that are either frankly elevated or inappropriately normal." (PMID 33925967, 2021).
Hypercalcemia (continued). "Its mutations jeopardize the activity of 24-hydroxilase and induce elevated serum calcitriol concentration that in turn causes hypercalcemia, hypercalciuria, and suppressed PTH secretion." (PMID 34959915, 2021). "Milder phenotypes are summarized as neonatal hyperparathyroidism (NHPT) and refer to infants with elevated serum PTH levels and resulting bone disease, but only modest hypercalcemia, usually based on heterozygous inactivating mutations of CaSR." (PMID 34659108, 2021). "Here we report a case of non-PTH-dependent hypercalcemia that occurred in a man with acromegaly and discuss potential mechanisms underlying development of hypercalcemia." (PMID 33933067, 2021). "Clinically this presents as generally asymptomatic hypercalcaemia, inappropriately detectable concentrations of PTH, associated with reduced renal calcium excretion." (PMID 33614549, 2021). "We searched PubMed systematically for reports relating to non-PTH-dependent hypercalcemia associated with acromegaly." (PMID 33933067, 2021). "Hypercalcemia associated with acromegaly is mostly parathyroid hormone (PTH)-dependent, being caused by parathyroid hyperplasia or adenoma, which are common in individuals with multiple endocrine adenomatosis-1 (MEN-1)." (PMID 33933067, 2021). "Primary hyperparathyroidism (PHPT), a leading cause of secondary osteoporosis, is characterized by hypercalcemia and bone loss owing to the overproduction of parathyroid hormone (PTH)." (PMID 34574045, 2021). "PTHrP secretion should be considered in patients with NETs and hypercalcemia associated with low PTH levels." (PMID 34093441, 2021). "After delivery, there is a risk of severe hypercalcemia in women with PHPT who are lactating as PTH-rp production will increase." (PMID 33544354, 2021). "The severity of hypercalcemia caused by elevated serum parathyroid hormone (PTH) levels determines the symptomatology." (PMID 34450530, 2021). "Hypercalcemia due to calcitriol secretion is diagnosed in the presence of high levels of 1,25-dihydroxyvitamin D, associated with low PTH levels, and high phosphorus levels." (PMID 34093441, 2021). "The presence of alterations in mineral metabolism, as hypercalcemia,hyperphosphatemia and PTH extremes is another risk factor." (PMID 34910803, 2021). "Here we present a case of non-PTH-dependent hypercalcemia associated with a growth hormone- (GH) and prolactin- (PRL) co-secreting pituitary macroadenoma." (PMID 33933067, 2021). "Causes of hypercalcemia can be broadly divided into parathyroid hormone (PTH) dependent and PTH-independent etiologies." (PMID 34322336, 2021). "It has been documented that Cinacalcet has the advantage of quick onset in declining serum calcium, serum phosphorus, and PTH, meanwhile, reduce volume and size of parathyroid glands, hardly causing hyperphosphatemia and hypercalcemia." (PMID 34368073, 2021). "Although the underlying cause can be osteolytic metastases, hypercalcemia of malignancy is usually caused by secretion of an active peptide such as parathyroid hormone-related peptide (PTHrP), parathyroid hormone (PTH) or calcitriol." (PMID 33413267, 2021). "The prevalence of hypercalcemia in two recent studies was around 15% and was always associated with PTH disturbances." (PMID 33909856, 2021). "Using next generation sequencing, we screened for mutations in 185 patients with PTH levels < 20 pg/mL, hypercalcemia and/or hypercalciuria, and relatives." (PMID 34721296, 2021). "This reduction can be seen in the PTH-induced hypercalcemia in both cases of PTH-induced hypercalcemia associated with kidney failure or diet-provoked hyperparathyroidism." (PMID 32963524, 2020). "The hypercalcemia was associated with normal plasma phosphate and vitamin D concentrations, and a high parathyroid hormone level, with an abnormal fixation of the lower lobe of the thyroid on sesta-methoxy-isobutyl-isonitrile scintigraphy." (PMID 32792004, 2020).